TLR4 (toll like receptor 4)
Diseases named in the same sentence as TLR4 in open-access papers (continued):
Sharing a sentence is not in itself a finding about the gene and the disease.
tumor (continued). "TLR4 expression does not affect the tumor-infiltrating immune cell profiles but regulates the expressions of the metabolic enzymes and ATP production that underlie how TLR4 promotes the CRC growth under HFD conditions." (PMID 34385421, 2021). "Furthermore, the expression of Tlr2 and Tlr4 in both hematopoietic and stromal compartments appears to support Mmp2-driven tumor growth." (PMID 34032639, 2021). "Among other receptors, HA binds the TLR4 promoting tumor growth and differentiation." (PMID 34360868, 2021). "TLR4 is a pattern recognition receptor (PRR) family member that confers the ability to “sense” damage signals, and activates innate immunity, that can amplify the tumor-associated inflammation." (PMID 34195201, 2021). "Conversely, the reduction of LPS trough intestinal decontamination with antibiotics, gut microbiota modulation by probiotics or genetic ablation of its receptor toll-like receptor 4 (TLR4) in mice are protective against tumor growth, representing potential targets for HCC prevention." (PMID 34204274, 2021). "TLR4 expressed by DCs facilitates the activation of tumor-specific T cell immunity." (PMID 34660305, 2021). "Furthermore, TLR4 signaling has been linked to HCC invasion, multidrug resistance, tumor angiogenesis and metastases, and TLR4 antagonists suggested as therapeutic modalities for HCC." (PMID 34025657, 2021). "Overall, existing literature suggests that relative corticosteroid-induced immune cell depletion (comparing to other tumors), along with low load of immunogenic molecules, such as MHC II and TLR-4, and a high load of T-suppressive CD 276 interfere with the host’s anti-tumor response." (PMID 33918733, 2021). "Interestingly, the expression of TLR4 is strongly upregulated in colonic tissues of BALB/c mice treated with azoxymethane/dextran sodium sulphate (AOM/DSS) to induce IBD-CRC, and blocking TLR4 signaling slows the development of the tumor." (PMID 34744751, 2021). "In the process of tumor progression, the cg14629571 site dominates the expression of TLR4." (PMID 34141706, 2021). "Thus, active MPyV replication contributes to tumor formation also via a TLR4-driven chronic inflammatory response." (PMID 33923020, 2021). "Expression of TLR2 and TLR4 in the hematopoietic compartment aids tumor development." (PMID 34032639, 2021). "High TLR4 levels maintain the immune response and anti-tumor microenvironment." (PMID 34141706, 2021). "Although the ICD-induced anti-tumor response ultimately relies on CD8+ T cells, intact toll-like receptor 4 (TLR4) signaling in tumor-infiltrating innate immune cells, such as DCs, is required since the danger signals or TLR agonists are first perceived by innate immune cells." (PMID 34830850, 2021). "In the process of tumor initiation or progression, different tumors may have different degrees of the TLR4 involvement." (PMID 34631699, 2021). "Additionally, LPS activate TLR-4 of cancer cells and assist tumor cells immune-escape by preventing the action of cytotoxic T cells or natural killer (NK) cells." (PMID 35003015, 2021). "Moreover, the expression of TLR4 is lower in the elderly, high grade tumors, higher tumor stage, and progressive tumors." (PMID 34141706, 2021). "Moreover, inflammatory receptors such as TLR4 are also expressed in tumor cells, adding another layer of complexity that results from potentially distinct effects of TLR4 downstream signaling in each cell compartment." (PMID 33446690, 2021). "Moreover, gastric cancer cell-derived exosomes that contain HMGB1, activate the TLR4/NFκB pathway in the neutrophils, resulting in increased autophagy and induction of the pro-tumor activity." (PMID 34572138, 2021). "S100A9 might also interact with Toll-like receptor 4 (TLR4) expressed on tumor cells where it promotes tumor growth." (PMID 34572138, 2021).
tumor (continued). "The triggering of this pathway generated a deleterious inflammatory contexture that helped the tumor escape from immune surveillance and supported a pro-metastatic environment, demonstrating a role for the TLR4 engagement by tenascin-C for tumor growth and spread." (PMID 33718177, 2021). "miRNA 6869-5p-targeting TLR4/NFkB signaling acts as a tumor suppressor in CRC." (PMID 34385421, 2021). "Therefore, we shortlisted TLR4 for the study and further validated its expressions in the tumor tissues by qPCR." (PMID 34385421, 2021). "Interestingly, our data also showed that knockout of TLR4 abolished the HFD-enhanced β-catenin expressions in the tumor tissues, suggesting that the energy homeostasis regulated by β-catenin in CRC under HFD conditions is in relation to TLR4 activity." (PMID 34385421, 2021). "Considering that the activation of DNA repair cascade may increase tumoral cell fitness, with consequent enhancement of tumor cell survival, we tested the impact of inhibiting this cascade in this model of TLR4-LPS stimulation." (PMID 33446690, 2021). "30% ~ 40% CAFs are generated from endothelial cells through endothelial-to-mesenmal transition, and could secrete HSP90α to induce M2 polarization and promote tumor progression, which can be abrogated by Octyl gallate by blocking HSP90Α-TLR4 ligation." (PMID 34625124, 2021). "In this context, we aimed to analyze the impact of TLR4 stimulation in a MES-GBM tumor cell." (PMID 33446690, 2021). "Overall, TLR-4 may promote or inhibit tumor, depending on the tumor type, the stimulator of the receptor, and also the situation of the host." (PMID 34904014, 2021). "Our studies further certified that deficiency of CXCL10/TLR4 or TLR4 inhibitors could effectively reduce the monocytic MDSC recruitment with decreased MMP14, leading to the smaller tumor occupation." (PMID 33990548, 2021). "Compared to wild-type mice, knockout of CXCL10 or TLR4 significantly inhibited tumor development." (PMID 33990548, 2021). "To determine whether Tlr2 and Tlr4 signaling is required for tumor progression, we monitored tumor incidence and growth up to 19 days following B16 F1 injection in WT, Tlr2–/–, Tlr4–/–, and DKO mice." (PMID 34032639, 2021). "Our preliminary observation suggests that the current panel of biomarkers used in clinical practice (tumor mutation burden, microsatellite instability, and PDL-1 status) could be complemented with other potential biomarkers, such as TLR-4." (PMID 33911192, 2021). "Since mice received high-fat dietary intervention, we studied the lipid profiles of the tumor tissues and examined whether the lipid changes would affect the TLR4 expressions." (PMID 34385421, 2021). "The expression level of the TLR4 gene was also related to the OS of KIRC, SKCM, STAD, TGCT, and UCEC, which indicated that TLR4 expression could be used as a predictor of tumor prognosis." (PMID 34631699, 2021). "Toll-like receptor 4 (TLR4) is a pivotal mediator of dendritic cell activation via recognizing danger-associated molecular patterns (DAMP), and it is critical for the process and presentation of tumor antigens." (PMID 32756339, 2020). "We hereby show the interaction of fetuin‐A with TLR4 on the surfaces of adhered tumor cells." (PMID 33073533, 2020). "Whether TLR4 expression is positively correlated with STAT3 activation in tumor-infiltrating immune cells is a question to be addressed." (PMID 32312954, 2020). "TLR4 involved in tumor occurrence and development by inducing M2 macrophage infiltration and angiogenesis in tumor microenvironment and participating in the process of apoptosis, MyD88-dependent and independent signal transduction, or other biological processes." (PMID 32351566, 2020). "However, AAT induced TLR4 levels and enhanced LPS effects on the production of IL-6, a tumor-promoting cytokine." (PMID 32533048, 2020). "Indeed, blockade of TLR4 in TAMs with antibody reduces the production of cytokines and weakens their pro-tumor activity." (PMID 33224886, 2020).
tumor (continued). "Altogether, the anti-tumor activity, stimulation of DC maturation, and TLR4 signaling activation of tilianin were all blocked by the action of TLR4 siRNA and p65 siRNA, which indicated that tilianin exerted anti-tumor activity and tumor cell immune escape inhibition via TLR4 and p65." (PMID 32194422, 2020). "In addition to immune cells, tumor cells express TLR4, where it acts as a double-edged sword on tumorigenesis." (PMID 32023919, 2020). "Tumor-initiating stem cell-like cells (TICs) also express the overlapping progenitor genes and uniquely possess self-renewing and tumor-initiating properties due to intrinsic TLR4-Nanog oncogenic pathway." (PMID 33173221, 2020). "The data suggest mechanisms by which TLR4 modulates the adhesion and growth of tumor cells." (PMID 33073533, 2020). "Furthermore, tumor-derived HSPs activate TLR4 signaling in TAMs to produce cytokines that are beneficial to tumor growth, such as TNF-α and VEGF." (PMID 33224886, 2020). "Furthermore, immunohistochemistry showed that iNOS, IL-6, MIP-3α and VEGF expression was positively correlated with TLR4 levels in transplanted tumor tissue in a TLR4-dependent manner." (PMID 32095158, 2020). "Furthermore, the TLR4–Cxcl10 axis in ATMs promoted T cell recruitment, and M1-like macrophages stimulated T cell activation in tumor-seeded fats." (PMID 33060562, 2020). "Here, TLR4 expression in the transplanted tumor tissues was analyzed by immunohistochemistry." (PMID 32095158, 2020). "Furthermore, this group identified the relationship between HMGB1 and TLR4, in which HMGB1 plays an important role in the activation of DCs through TLR4 for efficient presentation of tumor antigens from dying cells." (PMID 33299138, 2020). "Moreover, CD14 and TLR4 expression involved in endotoxin signaling was downregulated in PBMCs and tumor-derived cells." (PMID 32425932, 2020). "However, few clinical trials have tested the anti-tumor potential of the agonist TLR4, known to induce the production of iNOS and NO." (PMID 32370259, 2020). "However, the current paradigm of the immunogenicity of hyperthermia mainly relies on HSPs and activated Toll-like receptor-4 (TLR-4) signaling pathways for the initiation of tumor-specific immune responses." (PMID 33240283, 2020). "A strong TLR4 expression in the tumor served as an independent prognostic factor." (PMID 32424768, 2020). "In addition, activation of TLR2 by endogenous extracellular matrix-derived proteoglycan versican and TLR4 by HMGB-1 from damaged cells are known to promote tumor growth in a context-dependent manner." (PMID 32422978, 2020). "COLEC12 could reduce TLR4 expression, weaken NF‐κB and C3 signaling pathway to release inflammatory factors downstream, restrain immune defense to tumor cells, inhibit apoptosis of tumor cells, and cut down lives of mouses." (PMID 32822099, 2020). "Besides reducing the accumulation and expansion of MDSCs, AMPK activation also attenuated the immunosuppressive function of tumor MDSCs through TLR4/Myd88 pathway." (PMID 33613512, 2020). "Thus, senescence and an activated TLR4 signalling pathway likely promotes tumour growth through the generation of inflammatory niche which selects for invasive paclitaxel resistant CSC populations leading to shorter survival time in patients." (PMID 33370338, 2020). "The ApcMin/+ TLR4−/− group displayed fewer tumours than the ApcMin/+ WT group." (PMID 31650683, 2020). "In conclusion, Selene could target the mitochondria of tumor cells via the TLR4/TRAF3/MFN1 pathway, induce tumor cell apoptosis, and inhibit inflammatory cytokine secretion in ascites." (PMID 32802180, 2020). "The results showed that miR-203 mimics could lead to a downregulation of TLR4 compared with the control group, while miR-203 inhibitors could reverse the downregulation of TLR4, thus suggesting that tumor-derived exosomes interfere with DCs via miR-203." (PMID 33142779, 2020).
tumor (continued). "Neither TLR2 nor TLR4 immunoexpression associated with patient age, the histological type of tumor, or the Dukes tumor stage." (PMID 32424768, 2020). "In another cohort of Chinese OSCC patients, cytoplasmic TLR-4 expression was significantly increased in the tumour tissues and was correlated with deeper tumour invasion (p = 0.008), poor differentiation (p = 0.034), and an advanced pathologic TNM stage (p = 0.008)." (PMID 33008143, 2020). "Elevated TLR2 and TLR4 levels were observed in lung neutrophils from tumor-bearing mice." (PMID 32943604, 2020). "Multiple effects had been identified of TLR4 in tumor progression." (PMID 33363472, 2020). "Calreticulin serves as an “eat me” signal, ATP recruits dendritic cells to the tumor sites to cause their maturation to antigen-presenting cells, and HMGB1 facilitates the Toll-like receptor 4 dependent cross-presentation of the released tumor antigens to cytotoxic T-cells." (PMID 32781554, 2020). "In the Cox multivariate survival analysis adjusted for age, gender, Dukes stage, the tumor grade, and tumor location, a moderate TLR4 immunoreactivity (HR 0.66, 95% CI 0.49–0.89, p = 0.007) compared with a strong TLR4 tumor expression served as an independent prognostic factor." (PMID 32424768, 2020). "And Paclitaxel promoted tumor MDSCs differentiation into mature DCs in a TLR4-independent manner." (PMID 33613512, 2020). "Interestingly, as seen with CpG-ODN, in a model of B cell lymphoma, G100 induced a protective CD8+ T cell response that was dependent on tumour cell expression of TLR4." (PMID 33352882, 2020). "Moreover, the expressions of TLR4, MyD88, and P-NF-κB p65 in subcutaneous tumor tissues from the USP13 knockdown group were prominently lower than those in the control group (P < 0.05)." (PMID 33195243, 2020). "In addition, gut microbiota-derived lipopolysaccharides (LPS) promote tumor progression in liver cancer by activating the TLR4 signaling." (PMID 32817793, 2020). "Interestingly, Toll‐like receptor (TLR4), a molecular functioning in tumour microenvironment (TME), demonstrated the same expression trend." (PMID 32329191, 2020). "Furthermore, ribosomal family proteins have been shown to activate immune cells after binding to TLR4 and to induce inflammation within the tumor microenvironment." (PMID 33299138, 2020). "Among patients with a Dukes B tumor, a strong TLR4 immunoexpression indicated a worse prognosis." (PMID 32424768, 2020). "Then, the direct effect of TLR4 on tumor growth was observed carefully." (PMID 32095158, 2020). "In a previous study, we found that crude polyporus polysaccharide could suppress the growth of tumor cells via the TLR4/NF-κB pathway and greatly induce the transformation of M2 subtype macrophages to the M1 subtype in vitro." (PMID 32850623, 2020). "Indeed, downregulation of ATG7 in OSCC cells augments tumor cell migration through a mechanism dependent on Toll-like receptor 4, TLR4, a protein highly expressed during poor prognosis OSCC." (PMID 33363032, 2020). "Exposition of TLR-4 on LPS in in vitro studies resulted in tumor-cell-line progression." (PMID 32354122, 2020). "In a similar manner, the toxic side effects of anticancer radiation therapy (RT) and chemotherapy have been found to be caused in part by activation of TLR4 signaling by endogenous protein HMGB1 released by activated immunocytes and tumor cells under stress conditions." (PMID 32027657, 2020). "Moreover, Fas and TLR-4 contemporary activation results in the disappearance of TLR-4 tumor-promoting properties." (PMID 32354122, 2020). "The TLR4–Cxcl10 axis in ATMs/TAMs played a central role in the recruitment of T cells, and TLR4-mediated M1 macrophage activation was critical for T cell activation in tumor-seeded eFats." (PMID 33060562, 2020). "Interestingly, platelets interacting with tumor cells through the TLR4 axis can also activate NETs formation through a P-selectin-dependent mechanism, further amplifying thrombosis." (PMID 33042789, 2020).
tumor (continued). "However, further studies are needed to understand interaction between TLR4 and granulocyte-tumor cell intercellular signaling pathways." (PMID 30934946, 2019). "We further proved that ß-lap induced ICD and activated innate sensing via an HMGB1/TLR4 pathway and upregulated the type I IFNs signaling in the tumor microenvironment, resulting in the promotion of Batf3 DCs to cross-prime T cells and activate of antitumoral adaptive immune response." (PMID 31324798, 2019). "Uric acid and heat shock proteins could bind to scavenger receptor-A and toll-like receptor 4 on DCs and allow DCs to present tumor antigens to elicit immune responses." (PMID 31008116, 2019). "HMGB1 may also be released from tumor cells dying upon chemo- or radiotherapy therefore stimulating and TLR4 leading to DC maturation." (PMID 31695691, 2019). "This suggests that TLR4 is a biomarker of interest for tumor metastasis and prognosis." (PMID 31240216, 2019). "In fact, TLR4 has been reported to play divergent roles, either as a pro- or an anti-tumor agent." (PMID 31318878, 2019). "Our results show that the activation of TLR4 supports tumor progression by promoting the release of more effective immunosuppressive exosomes, although differences were observed depending on the origin of the tumor." (PMID 31186484, 2019). "TLR4 in particular is an essential receptor for LPS recognition, which may further tumor progression since it is highly expressed in CRC." (PMID 31450675, 2019). "Similarly, in Tlr4−/− and Myd88−/− mice there were much less tumor reactive T cells in the control group compared with that in WT mice." (PMID 31324798, 2019). "In colorectal cancer TLR4 activation protects tumor cells by preventing their lysis." (PMID 30976817, 2019). "In addition to TLR9-mediated tumor DNA sensing, we have previously found that TLR4 also promotes activation of tumor-specific CTLs after chemotherapy by recognizing the chromatin-associated factor HMGB1 released from dying tumor cells." (PMID 31619293, 2019). "Otherwise, the relatively high homology between STPIs from different origin and their potential effect on immunonutritional processes that may influence TLR4 signaling and the tumor environment have been studied to a much lesser extent." (PMID 30774778, 2019). "In cervical cancer TLR4 was found to promote proliferation and apoptosis resistance of tumor cells." (PMID 30976817, 2019). "Co-IP assays and mass spectrometric analyses indicated that TRIM44 overexpression induces cell EMT through activating AKT/mTOR pathway via directly binding and stabilizing TOLL-like receptor 4 (TLR4), and TLR4 interference impeded TRIM44 induced tumor progression." (PMID 30922374, 2019). "Finally, rapamycin was used for targeting TLR4, which triggered immune escape of tumor cells and inhibited the TLR4-activated NF-κB signaling pathway, uncovering a novel mechanism behind the antitumor effects of rapamycin." (PMID 31775797, 2019). "Moreover, the addition of a TLR4 inhibitor in the co-culture of HC-MSC with MM cells prevented the activation of the pro-tumor activity in PC-educated MSC." (PMID 31541083, 2019). "Similarly, there is research confirming that TLR4 can promote tumor-specific cytotoxic T cell responses." (PMID 31531018, 2019). "They thus offer new insights into potential new strategies for MM therapy as it is can be assumed that TLR4 targeting could limit tumor burden and provide an adjuvant therapy to standard treatments." (PMID 30824741, 2019). "In the case of TLR4 polymorphisms, Asp299Gly (rs4986790) and Thr399Ile (rs4986791) were shown to be associated with tumor progression, however, no direct association of these SNPs was found in case-control set up33,34." (PMID 31278284, 2019). "The results showed that blockade of HMGB1 signaling diminished the antitumor effect of β-lap, indicating that β-lap may induce HMGB1 release in the tumor microenvironment to enhance innate response via a TLR4/MyD88 pathway." (PMID 31324798, 2019).